EPO (erythropoietin)
Diseases named in the same sentence as EPO in open-access papers (continued):
Sharing a sentence is not in itself a finding about the gene and the disease.
anemia (continued). "In response to cellular hypoxia, a regulatory increase in renal EPO secretion in patients with anemia would be expected." (PMID 36211426, 2022). "Elevated hepcidin was observed in patients with renal impairment and plays a role in iron metabolism in inflammation-related anemia through the interaction of erythropoietin, iron, and bone marrow." (PMID 35628912, 2022). "Anti-inflammatory molecules injections, creatine supplementation or erythropoietin (EPO) administration to fight against anemia are under evaluation." (PMID 36358820, 2022). "Erythropoietin (EPO) is an endogenous hormone that is already being used in clinical practice for treating anemia." (PMID 35806125, 2022). "Subsequently, anemia is found to be related to uremic cardiomyopathy, and the protective effect of erythropoietin makes it the earliest therapeutic strategy for uremic cardiomyopathy." (PMID 35903671, 2022). "Erythropoietin levels that turned to be high possibly due to severe anemia in nephrectomized BKO drinking PBS induced greater degrees of bone loss." (PMID 35622784, 2022). "In the HF population, several pathomechanisms (e.g., congestion and related malabsorption, renal dysfunction and impaired erythropoietin production, general inflammation and frequent use of anticoagulants) are responsible for the development of anemia." (PMID 35204607, 2022). "Pathogenesis of anaemia in MM is related to bone marrow suppression of normal haemopoiesis and renal impairment leading to reduced erythropoietin secretion." (PMID 37092066, 2022). "In β-thalassemia, erythropoietin is dramatically increased in response to anemia and hypoxia with subsequent erythroid expansion in bone marrow resulting in bone deformity." (PMID 35622784, 2022). "Roxadustat is an oral anemia-correction agent function that increases endogenous erythropoietin by inhibiting propyl hydroxylase induced hypoxia-inducible factor degradation." (PMID 35445052, 2022). "Blood transfusions and EPO are usually used to treat or prevent anemia in a child, but this results in a high iron load and the formation of oxygen radicals, which causes retinal damage." (PMID 36589197, 2022). "Patients undergoing hemodialysis in Taiwan are entitled to use EPO treatment as long as they have anemia." (PMID 36077032, 2022). "In this prospective study, we characterized the biochemical profiles of common types of acquired anemia in children, with an emphasis on the less routinely evaluated factors: hepcidin, EPO and sTfR." (PMID 35177695, 2022). "Higher levels of inflammatory markers, interleukin-6, and leptin; hepcidin levels; ferritin levels; EPO levels; and reactive oxygen species (ROS) all contribute to the incidence of anemia in cancer patients." (PMID 35464620, 2022). "Conversely, reduced oxygen transport in anemia induces tissue hypoxia, which stimulates erythropoietin (EPO) production through activation of the HIF system." (PMID 35363823, 2022). "Pharmacist created in−hospital guidelines for proper use of recombinant human erythropoietin, provided drug information on CKD−associated anemia to physicians and nurses, performed intervention at the physician, drug, patient, and hospital level." (PMID 36141441, 2022). "Although erythropoietin levels improve after a successful kidney transplant, anemia persists in a large number of pediatric recipients." (PMID 35795334, 2022). "Anemia in lower-risk MDS is managed symptomatically with RBC transfusions and/or EPO-stimulating agents (ESAs), in particular, recombinant epoetin-alfa and beta." (PMID 36278584, 2022). "In response to hypoxia, HIF-1 mediates the activation of anaerobic glycolysis pathways, erythropoietin synthesis pathways (in anemia or individuals living at altitude), and production of VEGF (with new blood vessel formation as in chronic myocardial ischemia)." (PMID 35203690, 2022).
anemia (continued). "Except for the correction of anemia, EPO treatment in chronic renal failure patients improves depression, fatigue, muscle power, exercise ability, and neurocognitive function." (PMID 36077032, 2022). "Correspondingly, it was reported by another study that as the chronic renal disease progresses, erythropoietin synthesis is declining also, hypothetically leading to anemia." (PMID 34980089, 2022). "It is the first clinical trial to study the effect of erythropoietin in patients with anemia and acute kidney injury." (PMID 35279078, 2022). "Causes of anemia in CKD are complex, but a central feature is the deficit of erythropoietin (EPO) produced by the kidney during ESRD." (PMID 35937691, 2022). "The observed increase in erythroferrone (Erfe) is consistent with severe anemia and grossly elevated plasma EPO levels." (PMID 36110936, 2022). "EPO-stimulating agents (ESAs) have been used to treat anemia in these patients and have also been reported to improve cardiac function." (PMID 36140193, 2022). "Anemia can trigger a compensatory mechanism through increased release of the cytokine erythropoietin (EPO) into the blood to stimulate stress erythropoiesis in the spleen." (PMID 35678476, 2022). "At the beginning of the 90 s, following the release of the recombinant human erythropoietin (rhuEPO), transfusions' needs to treat anemia in chronic kidney disease patients were minimized." (PMID 35279078, 2022). "Another possible mechanism through which anemia affects bone is via elevated levels of EPO in the blood." (PMID 35739404, 2022). "Accumulating evidence have shown that the administration of iron and erythropoietin cannot improve anaemia or reduce the requirement of blood transfusion in critically ill patients." (PMID 36128261, 2022). "Patients with elevated RDW presented a higher prevalence of anemia and were more likely of receiving iron supplements, EPO stimulating agents, beta-blockers and calcium-channel blockers." (PMID 35755057, 2022). "Altitude-induced hypoxia reduces EPO requirements in ESKD patients with treatment-refractory anemia." (PMID 35453626, 2022). "We also include a discussion on a cytokine molecule erythropoietin (EPO), widely known and prescribed as a hormone to treat anemia but has recently been shown to function as a neurotrophic factor in the central nervous system (CNS)." (PMID 36081576, 2022). "The mechanism of action on anemia is mainly to promote the synthesis of EPO and improve iron metabolism, and it is also beneficial to the cardiovascular aspects of CKD patients." (PMID 36225579, 2022). "Currently, there is an ongoing phase 4 trial assessing the effect ROX versus recombinant human erythropoietin on patients with anemia and CKD (NCT04655027)." (PMID 35363823, 2022). "As well, the effects of erythropoietin (EPO)—given to MDS patients to combat anemia and defer blood transfusions—are suppressed by TNF-a, and it has been found that giving lenalidomide with EPO improves this unwanted suppressive effect." (PMID 35159389, 2022). "EPO expression is stimulated by a fall of the local oxygen tension as a consequence of arterial hypoxia or anemia." (PMID 35511367, 2022). "In anemia, EPO is also synthesized by the liver, but it cannot compensate for impaired renal production." (PMID 35806113, 2022). "One observational and one randomized controlled study both have identified that EPO treatment slows the onset of dialysis in DN-related anemia." (PMID 35453626, 2022). "Only 16.8% of the patients with anemia included in this study were treated with EPO, and only 17.4–22.8% of the patients with anemia were treated with iron, folic acid, vitamin B12, and other hematopoietic ingredients." (PMID 36349057, 2022). "It is interesting because the anaemia status is changed soon after HD start, with adequate EPO and iron replacement, targeting the same haemoglobin range for all patients along the follow-up period." (PMID 35196997, 2022).
anemia (continued). "Hepcidin prevents iron release from the macrophages by degrading ferroportin and contributes to anemia development independently from other factors, such as lower endogenous EPO production in the kidneys." (PMID 36558477, 2022). "Ineffective erythropoiesis in β-thalassemia leads to anemia and, subsequently, to tissue hypoxia and overexpression of EPO, which results in accumulation of early erythroid progenitors." (PMID 36278584, 2022). "Conversely, hemolysis, hemorrhage, anemia, and erythropoietin inhibit hepcidin, which enables the restoration of Fe resources and maintains effective erythropoiesis." (PMID 35211089, 2021). "Anemia in CKD is mainly attributable to the relative decrease in erythropoietin production by the kidneys, absolute or functional iron deficiency, and shortened red blood cell survival." (PMID 34217324, 2021). "They found patients with COPD and anemia also have elevated erythropoietin (EPO) levels, suggesting EPO resistance in COPD is related to inflammation." (PMID 34683114, 2021). "EPO secreted in response to anemia promotes the formation of erythroblastic islands in the spleen followed by the extensive proliferation of erythroid cells." (PMID 33669537, 2021). "Epoetin, the biosynthesized recombinant form of human erythropoietin, stimulates the production of red blood cells and is therefore used for the treatment of anemia." (PMID 33953678, 2021). "Erythropoietin (EPO) has long been used in preterm neonates to prevent and/or treat anemia of prematurity." (PMID 34912224, 2021). "While erythropoietin is commonly used to treat anemia, some patients exhibit a poor response to erythropoietin." (PMID 33907089, 2021). "Persistent anaemia after 4 weeks of iron and EPO therapy requires further evaluation for other possible contributing factors, such as copper, ceruloplasmin or vitamin B12 deficiency, followed by appropriate treatment." (PMID 33514942, 2021). "By contrast, in patients with CKD, EPO concentrations are inappropriately low for the degree of anemia." (PMID 33498292, 2021). "The treatment of anemia in CKD is mainly performed clinically using erythropoiesis-stimulating agents (ESAs) or erythropoietin (EPO) analogs." (PMID 34115611, 2021). "In this sense, some molecules of the HIF system have already been studied as new targets for anemia treatment with a view to increase endogenous EPO production and presumably improve the utilization of iron stores." (PMID 33842503, 2021). "Hemolysis and anemia in SCD can initiate an erythropoietin response and stress erythropoiesis, which triggers the expression of the erythropoietin-dependent GATA-1 gene, and in sickle red cell progenitors, an increased generation of miRNA-144." (PMID 34684143, 2021). "The links between anemia and diabetes and the complications can be partially explained by the influence of EPO, which apart from affecting the hematopoiesis has a number of other metabolic effects." (PMID 34708130, 2021). "In patients with chronic kidney disease (CKD), anemia develops gradually, which is primarily due to an inadequate synthesis of erythropoietin by the kidneys, as well as to iron disorders in the body, blood loss, shortened erythrocyte survival and inflammation." (PMID 33567688, 2021). "It is now recommended (low grade recommendation) by the French societies of critical care to treat anemia with erythropoietin in ICU." (PMID 33588893, 2021). "EPO deficiency is a determinant cause of anemia in CKD, as the kidney is the main source of EPO production." (PMID 34356833, 2021). "In certain pathological conditions such as chronic renal failure, EPO production becomes insufficient and anaemia ensues." (PMID 34142210, 2021). "Targeted deletion of EPO (EPO−/−) or EPOR (EPOR−/−) in mice results in embryonic death due to severe anemia." (PMID 34603036, 2021). "The anemia observed in Itai-itai disease patients was believed to be primarily the result of impaired production of EPO." (PMID 33429420, 2021).
anemia (continued). "Recombinant human erythropoietin (rHuEPO) is a biopharmaceutical drug given to patients who have a low hemoglobin related to chronic kidney disease, cancer or anemia." (PMID 33452310, 2021). "Erythropoiesis-stimulating agents, such as recombinant EPO, are currently the first line of therapy in low-risk MDS patients who develop transfusion-dependent or symptomatic anemia." (PMID 33467674, 2021). "Patients diagnosed as having chronic renal insufficiency are more likely to have anemia due to reduced EPO levels." (PMID 33888084, 2021). "Anemia has been correlated with decrease in libido, sexual desire, and erectile function with EPO therapy demonstrated to improve sexual desire and erection quality in HD patients." (PMID 33918412, 2021). "Although iron and erythropoietin deficiencies and hyporesponsiveness to the actions of erythropoietin are the major causes of anemia in CKD patients, anemia in diabetic patients with CKD result from one or more mechanisms." (PMID 34560842, 2021). "EPO administration to improve oxygen delivery and treat anemia in infants have been proposed by several studies, sometimes together with iron administration." (PMID 34912224, 2021). "Pure O2 breathing has been utilized to induce a NOP effect, associated with the increase in newly synthesized erythropoietin (EPO) targeting the treatment of anemia." (PMID 33466421, 2021). "In summary, Lin and colleagues managed to achieve a correction of anemia in a mouse model using human endothelial-based vascular grafts with erythropoietin overexpression after only 1 week." (PMID 33738695, 2021). "Anemia (73%) is attributed to a reduction in erythropoietin production and suppressive effects of excess cytokines on erythropoiesis." (PMID 33718400, 2021). "The ONS thus demonstrate to have multiple beneficial effects, specifically including the ability to allow a reduction of EPO therapy, a fundamental tool for the anemia treatment in the CKD patient." (PMID 33406683, 2021). "Persistent anaemia after 4 weeks of iron and erythropoietin therapy requires further evaluation for other possible contributing factors, such as copper, ceruloplasmin or vitamin B12 deficiency, and appropriate treatment." (PMID 33514942, 2021). "Theoretically, the patients most prone to develop IO are patients that have uncompensated anemia, since these patients have reticulocytosis and persistently elevated EPO levels." (PMID 33672223, 2021). "Administration of recombinant EPO or EPO-stimulating agents increases red blood cell production and relieves anemia these patients." (PMID 34681039, 2021). "Serum levels of erythropoietin and hepcidin, leading to erythropoiesis or secondary anemia, respectively, showed a positive correlation with the amounts of PBCECs (r = 0.67 and 0.64, respectively)." (PMID 34257378, 2021). "G-CSF–induced repression of bone marrow erythropoiesis leads to anemia and hypoxia that stimulates the expression of erythropoietin by renal cells, which in turn enhances splenic erythropoiesis." (PMID 33234677, 2021). "Recombinant human erythropoietin (herein designated EPO) is widely used in clinical practice to treat anemia in patients with chronic kidney disease (CKD) and other disorders." (PMID 33475252, 2021). "In patients older than 45 years or with anemia, a number of factors can contribute to lower HbA1c levels, including declined nutrient metabolism, blunted erythropoietin response, and altered erythrocyte life span." (PMID 34055818, 2021). "While on dialysis to treat anaemia, the patient had received erythropoietin and iron intravenously, and the maximal serum ferritin level was 2115 ng/ml." (PMID 34051741, 2021). "The descriptive analysis revealed that the administration of heparin for anticoagulation, multivitamins for intravenous hyperalimentation, and erythropoietin injections for anemia in preterm neonates accounted for the majority of PHE-containing prescriptions." (PMID 34193299, 2021).
anemia (continued). "Anemia is a provoking factor in the progression of end-stage renal failure, and the treatment of anemia by erythropoietin can delay progression of renal failure." (PMID 34782668, 2021). "It is known that hypoxia occurring during anemia elicits production and release of EPO from the kidney and consequent extramedullary erythropoiesis in the spleen to try to compensate the anemic condition." (PMID 33525735, 2021). "Anemia remains one of the common complications of chronic kidney disease (CKD), which is due to the relative or absolute deficiency of erythropoietin (EPO), resulting in the inability to maintain normal red blood cell (RBC) levels." (PMID 34276361, 2021). "Erythropoietin (EPO), used to treat anemia, significantly inhibited the oxidation process, suggesting that anemia aggravates OS." (PMID 34249547, 2021). "These inhibitors block enzymatic activity of PHD to stabilize HIFs, whose accumulation leads to increased transcription and expression of EPO, followed by enhanced erythropoiesis to alleviate anemia in CKD patients." (PMID 33430279, 2021). "Due to ongoing hemolysis and insufficient compensation of anemia, EPO levels remain high, further stimulating erythroid output and high ERFE expression." (PMID 33672223, 2021). "Over the past 30 years recombinant human EPO and other erythropoiesis stimulating agents (ESAs) have been used successfully to treat anemia in millions of patients, predominantly in those with CKD." (PMID 33475252, 2021). "Nevertheless, serum levels of ERFE and EPO, along with erythropoietic activity and hepcidin, were higher in active rheumatoid arthritis patients who had anemia than in control patients." (PMID 34772005, 2021). "The newborn received the infusion of erythropoietin every seven days from the fortieth day of life; subsequently, the status of anemia underwent clinical resolution." (PMID 33757559, 2021). "When indicated, the use of human recombinant erythropoietin (rHuEPO) and iron supplementation is usually sufficient to correct anemia and is considered the standard of care." (PMID 34886434, 2021). "Recombinant human EPO has been reported to be safe and efficacious for the treatment of anaemia in children with nephrotic syndrome." (PMID 33514942, 2021). "Due to transfusion-dependent anemia in her subsequent pregnancy despite continuation of EPO, resumption of HC (15 mg/kg BW; GW 30) was mandatory prior to delivery (GW 34 + 4)." (PMID 34575647, 2021). "Recombinant human erythropoietin (EPO) is the main therapeutic glycoprotein for the treatment of anemia in cancer and kidney patients." (PMID 34523784, 2021). "Under ischemic stress, anemia, hypoxia at high altitude as well as other factors (tissue injuries, degeneration), the production of EPO is activated in the adult kidneys." (PMID 34440909, 2021). "Meanwhile, improve monitoring and calibration of erythropoietin stimulating agents to meet anemia targets." (PMID 33441625, 2021). "Granulocyte colony-stimulating factor (G-CSF) as primary prophylaxis was employed in 77 (43%) patients, human recombinant erythropoietin (rhEPO) was used due to disease-related anemia in 29 (16%) patients." (PMID 33808164, 2021). "In renal disease, anemia results from the failure of the diseased kidneys to produce adequate amounts of EPO, resulting in subsequent anemia." (PMID 34681039, 2021). "In CKD patients, the stabilization of HIF by PHD inhibitors can improve the EPO level and attenuate anemia, an observation leading to clinical use of PHD inhibitors." (PMID 33430279, 2021). "Patients benefited from the correction of anemia by erythropoietin administration and were divided into two groups, based on the target Hb value of 10 g/dL or 13 g/dL." (PMID 34441451, 2021). "At the very beginning, the rationale for their use was quite simple: there was one symptom, anemia; there was a new effective drug to cure it, recombinant human erythropoietin; therefore, it was administered to increase Hb levels." (PMID 33670704, 2021).